FUS (FUS RNA binding protein)
Diseases named in the same sentence as FUS in open-access papers (continued):
Sharing a sentence is not in itself a finding about the gene and the disease.
spinocerebellar ataxia type 2 (2 papers, 2019 to 2021). A subtype of type I autosomal dominant cerebellar ataxia (ADCA type I) characterized by truncal ataxia, dysarthria, slowed saccades and less commonly ophthalmoparesis and chorea. "Mutations in TDP-43 or FUS lead to ALS/FTD, while mutations in Ataxin-2 can cause spinocerebellar ataxia type 2 or ALS." (PMID 31138677, 2019).
Tremor (2 papers, 2020 to 2025). An unintentional, oscillating to-and-fro muscle movement about a joint axis. "Recently, a 19‐year‐old Japanese FUS‐ALS patient with p.P525L mutation displayed a rapid‐onset ALS co‐occurring with autism spectrum disorder and tremor." (PMID 32307925, 2020). "None of the FUS‐ALS patients had tremor, epilepsy, learning disability, mental retardation, or other developmental disorders, which have been reported in some patients carrying FUS mutations." (PMID 39976178, 2025).
adenoma (1 paper, 2026). A neoplasm arising from the epithelium. "In the rat PIT1-lineage adenoma cell lines GH3 (somatotroph subtype) and MMQ (lactotroph subtype), the downregulation of FUS resulted in a significant reduction in cell viability." (PMID 41510173, 2026).
astrocytoma (1 paper, 2022). "In the present study, we investigated cytoplasmic SG formation using various fluorescent protein-tagged mutant FUS proteins in a human astrocytoma cell (U251) model." (PMID 36606141, 2022).
brain tumour (1 paper, 2025). "We used an IUE model for brain tumour transformation to test the capacity of ZFTA-sub-FUS:IDR and ZFTA-sub-EWS:IDR to initiate tumours in mice." (PMID 40866513, 2025).
coronary heart disease (1 paper, 2020). "Here in this study, the role and interactions of lncRNA THRIL, AKT pathway and FUS in the development of coronary heart disease were investigated." (PMID 32907536, 2020).
diabetes (1 paper, 2023). "The incidents illustrated that, during the development of diabetes, FUS competes with miR-124-3p and SCOTIN to bind circGlis3, resulting in a decrease in circGlis3 by restricting diffusion in the cytoplasm via the recruitment function of FUS-formed SG." (PMID 36681689, 2023).
Down syndrome (1 paper, 2025). "Misclassification incidents involving FUS::ERG fusions, KMT2A rearrangements in older adults, and Down Syndrome-associated AML highlight critical gaps in training data availability." (PMID 40730747, 2025).
dyslipidemia (1 paper, 2018). "Finally, we need to better understand how the nuclear localization, aggregation, and phosphorylation of TDP-43 and FUS might be influenced by altered metabolic states, such as hyperglycemia and dyslipidemia, and how these states might protect neurons from damage." (PMID 30509290, 2018).
emotional dysregulation (1 paper, 2025). "FUS mutation carriers show a particularly high degree of disinhibition and emotional dysregulation, often leading to more severe behavioural disturbances than in other forms of FTD." (PMID 40649976, 2025).
enteroviral infection (1 paper, 2021). "In this study, we identified FUS as a novel host restriction factor against enteroviral infection." (PMID 33827951, 2021). "Our and other labs showed previously that some RBPs, such as TDP-43 and AUF1, exert antiviral effects on enteroviruses, and these findings prompted us to further investigate the relationship of another functionally and structurally related RBP, FUS, with enteroviral infection (3, –, 8)." (PMID 33827951, 2021).
Epstein-Barr virus infection (1 paper, 2020). An infection that is caused by Epstein-Barr virus. "In addition, functional enrichment analysis indicated that these clusters were associated with the ribosome and viral mRNA translation, RNA transport/spliceosome, circadian entrainment, MAPK signaling, Epstein-Barr virus infection and proteasome pathways in FUS-ALS pathogenesis." (PMID 32967368, 2020).
Ewing's sarcoma family tumors (1 paper, 2008). "The EWS-FLI-1 fusion protein is associated with 85–90% of Ewing's sarcoma family tumors (ESFT), the remaining 10–15% of cases expressing chimeric genes encoding EWS or FUS fused to one of several ets transcription factor family members, including ERG-1, FEV, ETV1 and ETV6." (PMID 18648544, 2008).
fibrosis (1 paper, 2024). the formation of excess fibrous connective tissue in an organ or tissue in a reparative or reactive process. "To evaluate the direct role of FUS nuclear translocation in fibrosis, we used mice that carry a mutation in the FUS nuclear localization sequence (FUSR521G) and the cell-penetrating peptide CP-FUS-NLS that we previously showed inhibits FUS nuclear translocation in vitro." (PMID 38488009, 2024).
focal segmental glomerulosclerosis (1 paper, 2024). A renal disorder characterized by sclerotic lesions in the glomeruli. "Finally, differential gene expression analysis and immunohistochemistry of tissues from individuals with focal segmental glomerulosclerosis or nonalcoholic steatohepatitis revealed significant upregulation of FUS and/or collagen genes and FUS protein nuclear localization in diseased organs." (PMID 38488009, 2024).
gastric tumors (1 paper, 2025). "Most gastric tumors with EWSR1/FUS::CREB fusions have been reported to be CCSLGT, also known as gastrointestinal neuroectodermal tumors (GNETs)." (PMID 40242428, 2025).
heart failure (1 paper, 2022). Inability of the heart to pump blood at an adequate rate to meet tissue metabolic requirements. "The lncRNA KCNQ1OT1 directly targets the FUS protein and negatively regulates its protein level, thus facilitating cardiomyocyte apoptosis in heart failure." (PMID 35974003, 2022).
hypopituitarism (1 paper, 2026). A condition of diminution or cessation of secretion of one or more hormones from the anterior pituitary gland. "In this study, based on the expression analysis and functional screening of PIT1-lineage PitNETs, we focused on the expression of the splicing factor FUS and revealed that its expression level was correlated with postoperative hypopituitarism." (PMID 41510173, 2026). "In patients with PIT1-lineage PitNETs, those whose tumors exhibited elevated levels of FUS demonstrated a significantly increased incidence of postoperative hypopituitarism." (PMID 41510173, 2026).
infarction (1 paper, 2020). A localised pathological necrosis of tissue resulting from obstruction of the blood supply usually by a thrombus, an embolus, or vascular torsion. "Furthermore, circFndc3b interacted with the RNA-binding protein FUS to positively regulate the expression of VEGF-A, thereby improving the function and reconstruction of the myocardium after infarction." (PMID 32419790, 2020).
ischemic stroke (1 paper, 2025). A stroke disorder caused by obstruction of blood flow to the brain, due to thrombotic (local blood clot formation) or embolic (due to a blood clot or other material traveling from another site) event. "By using the human brain tissue sections obtained from ischemic stroke patients, we found a consistent co‐localization between FUS, CD63, and the SGs marker protein G3BP1." (PMID 38924471, 2025).
Kaposi's sarcoma (1 paper, 2020). A malignant neoplasm characterized by a vascular proliferation which usually contains blunt endothelial cells. "Interestingly, FUS negatively regulates Kaposi’s sarcoma-associated herpes virus gene expression, revealing that FUS is a viral restriction factor." (PMID 32967368, 2020).
keratoacanthoma (1 paper, 2019). A dome-shaped, rapidly growing skin lesion composed of well differentiated squamous cells. "Prrx1-Cre; Rosa26 FUS-CHOP/+ mice developed keratoacanthomas shortly after birth." (PMID 31427882, 2019).
laryngeal carcinoma (1 paper, 2022). Carcinoma that arises from the laryngeal epithelium. "RIP assays further determined the potential RBP which binds with KIF26B-AS1 in laryngeal cancer, namely FUS." (PMID 36224753, 2022). "In our study, we researched the role of FUS in laryngeal cancer cells." (PMID 36224753, 2022). "We determined the co-localization of KIF26B-AS1 and FUS in cytoplasm of laryngeal carcinoma cells." (PMID 36224753, 2022). "Furthermore, KIF26B-AS1 plays an oncogenic role in laryngeal cancer via upregulating TLR4 expression as well as the FUS/TLR4 pathway axis, findings which offer novel insight for targeted therapies in the treatment of laryngeal cancer patients." (PMID 36224753, 2022). "However, the correlation of FUS with KIF26B-AS1 has never been reported in laryngeal cancer." (PMID 36224753, 2022).
lipoma (1 paper, 2015). A benign, usually painless, well-circumscribed lipomatous tumor composed of adipose tissue. "They considered that the presence of microscopic foci of lipoma-like or sclerosing areas, characteristic of WDLS, constitutes sufficient histologic evidence to exclude the diagnosis of MLS, as supported by the consistent absence of DDIT3 or FUS genomic rearrangements in such tumors." (PMID 25650275, 2015).
liver fibrosis (1 paper, 2024). "Pharmacologic inhibition of FUS nuclear translocation ameliorates CCl4-mediated liver fibrosis." (PMID 38488009, 2024).
memory impairment (1 paper, 2025). "Memory impairments are also pronounced in patients with FUS mutations, particularly affecting episodic recall, although short-term memory remains relatively preserved." (PMID 40649976, 2025).
mesothelial tumors (1 paper, 2024). "We demonstrated herein that EWSR1/FUS::ATF1 fused tumors should probably be considered as distinct mesothelial tumors." (PMID 39059063, 2024).
myxoid/round cell liposarcoma (1 paper, 2016). Myxoid/round cell liposarcoma (MRCLS) is a type of liposarcoma (LS) mostly located in the limbs, with a variable behavior depending on the histological subtype. "Thus, GFP-expressing MSC-5H (MSC-5H-GFP) cells give rise to spindle cell sarcomas (SCS); meanwhile, FUS-CHOP-expressing hMSCs (MSC-4H-FC and MSC-5H-FC) originate myxoid/round cell liposarcomas (MRCLS)." (PMID 27292183, 2016).
neuropathy (1 paper, 2021). A disorder affecting the nervous system that manifests with pain, tingling, numbness, and/or muscle weakness. "The changes we find in the inter-link patterns between FUSm and HspB8-WT or the neuropathy-causing mutant HspB8-K141E may appear counter-intuitive at first sight as far as they suggest a higher binding affinity of the mutant for FUS than the HspB8-WT." (PMID 34487489, 2021).
Obesity (1 paper, 2019). Accumulation of substantial excess body fat. "In the genomic locus covering rs1549293, the chromosomal interactions with FUS and HSD3B7 were observed to form each of 54 kb and 145 kb complexes, suggesting a regulatory role by this SNP to these obesity-associated genes (Pearson correlation coefficient r is 0.78 and 0.74, respectively)." (PMID 31494266, 2019).
oral cancer (1 paper, 2015). "In addition, our results also suggested interaction of hnRNPD with other RNA binding proteins (RBPs) such as ELAVL1, RALY, EWSR1 and FUS in oral cancer." (PMID 26318153, 2015).
osteogenesis imperfecta (1 paper, 2024). Osteogenesis imperfecta (OI) comprises a heterogeneous group of genetic disorders characterized by increased bone fragility, low bone mass, and susceptibility to bone fractures with variable severity. "In addition, somatic mutations in CREB3L1 contribute to osteogenesis imperfecta (OI), while the generation of Fused in sarcoma (FUS)-CREB3L1 and EWS RNA Binding Protein 1 (EWSR1)-CREB3L1 lead to LGFMS and sclerosing epithelioid fibrosarcoma (SEF) respectively." (PMID 38164349, 2024).
peripheral nerve injury (1 paper, 2026). Injury to a peripheral nerve. "Peripheral nerve injury upregulates circNrip1, but not Nrip1 mRNA, in injured DRG neurons, at least in part due to increased binding of the RNA-binding protein FUS to Nrip1 pre-RNA, thereby promoting circNrip1 formation." (PMID 41957537, 2026).
Primary lateral sclerosis (1 paper, 2022). "A few patients presented have been reported with pyramidal symptoms including spastic gait and speech indicative of primary lateral sclerosis (PLS) but the pathological diagnosis was PSP in the absence of any PLS-related pathologies, such as TDP-43 or FUS proteinopathies." (PMID 35911892, 2022).
retinoblastoma (1 paper, 2022). A malignant tumor that originates in the nuclear layer of the retina. "In addition, immunohistochemistry (IHC) showed positive staining for CD34 and heterogeneous retinoblastoma deficiency, and fluorescence in situ hybridization (FISH) showed no amplification of mouse double minute 2 homolog and no rearrangement of FUS or EWSR1." (PMID 36439417, 2022).
Rett syndrome (1 paper, 2018). A severe neurodevelopmental disorder affecting the central nervous system.
teratoma (1 paper, 2019). A non-seminomatous germ cell tumor characterized by the presence of various tissues which correspond to the different germinal layers (endoderm, mesoderm, and ectoderm). "Indeed, we identified up to 26 and 2 (FUS and NF2) loci when reprogrammed cells were produced with Lentiviral and Sendai methods respectively and no cancer associated-gene locus variations were found in teratoma generated with mRNA-derived hiPSCs." (PMID 31105870, 2019).
neurodegenerative disease (181 papers, 2011 to 2026). A disorder of the central nervous system characterized by gradual and progressive loss of neural tissue and neurologic function. "The RNA-binding protein Fused in Sarcoma (FUS), which is strongly implicated in both neurodegenerative disease and cancer, is known to interact with RNA molecules through a variety of GU-rich sequences." (PMID 41029441, 2025). "Intracellular aggregation of proteins such as Tau, TDP43, FUS, prion protein, and α-synuclein is a major hallmark of many major neurodegenerative diseases." (PMID 41278186, 2025). "Variants in FUS genes are causative or risk factors for several neurodegenerative diseases, including ALS and FTD." (PMID 38977621, 2025). "Hereditary mutations in FUS can be passed through generations, particularly affecting individuals with familial forms of neurodegenerative diseases like ALS." (PMID 40430041, 2025). "TARDBP (TAR DNA Binding Protein) and FUS (FUS RNA Binding Protein) are mRNA binding proteins linked to neurodegenerative diseases." (PMID 38255791, 2024). "In this context, decoding molecular mechanisms of LLPS and amyloid formation of TDP-43 and FUS is pivotal for unraveling the mystery of the associated neurodegenerative diseases and also bears critical clinical implications." (PMID 38029395, 2024). "Later, the association with neurodegenerative diseases gradually appeared, with missense mutations in FUS being the cause of some ALS, and subsequently, FUS was identified in ubiquitinated protein inclusions in the brain tissue of some FTLD patients." (PMID 38739933, 2024). "In summary, our study uncovers the critical role of FUS in mtDNA repair and provides new insights into the mechanisms of mtDNA damage and repair defects in FUS-associated neurodegenerative diseases." (PMID 38461154, 2024). "Most importantly, importins were attributed to counteract neurodegenerative disease by enhancing the solubility of nuclear proteins associated with pathological features such as FUS and TDP-436." (PMID 37296145, 2023). "Proteins associated with neurodegenerative diseases, such as FUS, Tau, TDP-43 and α-Synuclein, can transition from liquid droplets to solid droplets and then into amyloid-like or amorphous protein aggregates." (PMID 36835140, 2023). "TDP-43 (TAR DNA-binding protein 43), another hnRNP, which, similar to FUS, is heavily implicated in the etiopathology of several neurodegenerative diseases including ALS and Alzheimer’s disease, also plays an important role in NHEJ-mediated DSB repair." (PMID 34026839, 2021). "For example, FUS, an RNA-binding protein associated with several neurodegenerative diseases, forms “spherical droplets” in the neuronal nuclei, while its recombinant, purified form forms similar phase-separated “liquid droplets” in vitro." (PMID 32371601, 2020). "A growing number of studies have shown that FUS mutations in prion-like domains mediate the aggregation of FUS, which is an important reason for the development and progression of most neurodegenerative diseases." (PMID 31022909, 2019). "FUS is an RNA-binding protein that is mutated and/or aggregated in several neurodegenerative diseases; this study shows that both ATP and nucleic acids modulate liquid-liquid phase separation of FUS in the same manner by specific binding." (PMID 31188823, 2019). "All the suppressors were DNA/RNA binding proteins, like FUS, and had not been implicated as suppressors of toxicity caused by other neurodegenerative diseases proteins, indicating that these proteins are specific to FUS." (PMID 30002616, 2018). "Not only mutated FUS has been implicated in the progression of neurodegenerative diseases, wild-type FUS has also been observed to abnormally aggregate and contribute to a disease phenotype." (PMID 30002616, 2018). "FUS is a prion-like protein containing intrinsically disordered domains, and mutations in the FUS gene are implicated in causes of the neurodegenerative disease ALS." (PMID 26927092, 2016).